CD2 (CD2 molecule)
Diseases named in the same sentence as CD2 in open-access papers (continued):
Sharing a sentence is not in itself a finding about the gene and the disease.
infection (continued). "The proportion of the CD2+CD8α— γδ T cell subset was comparable to GF animals in all three infections." (PMID 25186625, 2014). "PRRSV caused a large increase in the proportion of lymphocytes at the site of infection and rapid differentiation of B cells leading to a high level of Ig-producing cells but a severe reduction in CD2—CD21+ primed B cells." (PMID 25186625, 2014). "For both IL-6 and CD2 blocking, the antibody was refreshed 1-day post-infection." (PMID 37202790, 2023). "To further determine whether this CD2-mediated inhibition of HIV-1 early infection steps can be alleviated by lymphatic cytokines, we cultured resting CD4 T cells in IL-2 or IL-7 for 3 days and then latently infected cells with HIV-1." (PMID 34765923, 2021). "In contrast, mice deficient in only CD2 or CD28 are not susceptible to spontaneous infection, although CD28-deficient mice can be infected when directly inoculated." (PMID 33669726, 2021). "Moreover, frequencies of CD2+CD8α+ γδ T cells increased in ileum of gnotobiotic pigs following colonization with probiotic Lactobacilli or infection with human rotavirus, while CD2+CD8α− frequencies decreased." (PMID 32612605, 2020). "Also, 627 gene probes were regulated by treatment or infection with either Dex or CD2-a + Dex, while 3,955 were regulated by either CD2-a or CD2-a + Dex." (PMID 29867993, 2018). "If so, does HIV preferentially infect CD2hi cells or does CD2 become upregulated after infection?" (PMID 30455699, 2018). "We observed a 47-fold increase in CD2+ T cells in the meninges by 12 days post infection (dpi)." (PMID 25881126, 2015). "Upon infection, all animals showed a down regulation of CD2 + CD21+ cells (phenotype of naïve B-cells), this could be either due to depletion or an indication of B-cell activation." (PMID 25073480, 2014). "The cell surface glycoprotein 2B4 (CD244) is related to CD2 and is implicated in the regulation of NK- and T-cell function and it was expressed on D21, but not earlier during infection." (PMID 21249199, 2011). "Eight days postinfection, an increase in T-bet– and IFN-γ–expressing CD4 T cells was detected in CD2-specific Egr2/3−/− mice, suggesting that the high levels of T-bet–expressing T cells in CD2-specific Egr2/3−/− mice result from hyperactivation of T cells at late stages of infection." (PMID 28455436, 2017). "Consistent with the results from CD2-Egr2/3−/− mice, Egr2/3-deficient retrogenic OT1 cells had severe defects in proliferation but were highly activated and produced excessive levels of effector cytokines compared with WT retrogenic-OT1 cells in response to OVA-VVWR infection." (PMID 28487311, 2017). "Furthermore, the difference in infection rates between CD2+ and CD2low T cells remained." (PMID 28953327, 2017). "Highly virulent ASFV Armenia08 infection decreased the numbers of CD8 + effector T cells and all γδ T cell subpopulations, namely, CD2−CD8− T cells, CD2 + CD8− T cells, and CD2 + CD8 + T cells." (PMID 34566910, 2021). "Differentiated effector γδ T cells (characterized by simultaneous expression of CD2 and CD8) increased after second infection only." (PMID 31539406, 2019). "PBMC were exposed to R2.5, CD2.5, WD2.5, R10, CD10 or WD10 followed by infection with M. tb MOI1 or stimulation with PPD." (PMID 31295271, 2019). "By normalizing CFU counts to the 3 h post-infection, macrophages were able to eliminate AIEC strains CD2-a, NRG857c, and HM605 at 72 h post-infection, with the HB101 strain easily eliminated 24 h post-infection." (PMID 29867993, 2018). "In the CD2+ CD4+ cell population, 2.24% were p24+ whereas infection rates of the CD2low CD4+ cells were with 10.33% nearly 5-times higher." (PMID 28953327, 2017). "CD2-Egr2/3−/− mice had severe inflammatory pathology in the lungs after i.n. infection with OVA-VVWR, whereas lung inflammation and mononucleocyte infiltration in infected lungs were much milder in CD2-Egr2 transgenic mice compared with WT counterparts." (PMID 28487311, 2017).
infection (continued). "To test for this, we first plotted the infection rates of CD2+ PBMC, CD2+ CD3+ T cells and CD2+ CD4+ cells of HIV-1 patients controlling the infection or showing a progressive course of infection." (PMID 28953327, 2017). "Mirsky and coworkers reported that the infection rate was approximately 40-fold higher for CD5+ B cells than for CD2+ T cells (121 ± 244 for CD5+ B cells and 3 ± 6 for CD2+ T cells), suggesting that B cells are the only PBMCs significantly infected by BLV." (PMID 23641811, 2013). "Their involvement ranges from serving as co-receptors for cell entry (CCR1 and CCBP2), mediating trans-infection (DARC), activating immune cells (CD97) to inducing viral production from latently infected cells (CSF3R, TNFRSF3 and CD2)." (PMID 20967291, 2010). "CD2 and subsequent CD8 expression on the cell surface of γδ T cells resembles activation and maturation steps, the former being observed 14 days after first and one day after second infection with H1N1pdm09." (PMID 31539406, 2019). "Strikingly, we found that the infection with HeV and NiV-B did not modify the expression levels of lymphocyte markers (CD2, CD3D, CD3E, CD3G, CD4, CD8A and CD27) in the lung tissue by 5 dpi." (PMID 29538374, 2018). "No clear infection-related changes were found in the CD2-defined γδ T cell subsets analysed in lymph nodes." (PMID 28559930, 2017). "Analysis of γδ T cell subpopulations in the MLN revealed no significant change in the proportion of CD2+CD8α— γδ T cells in any infection." (PMID 25186625, 2014). "Interestingly, infection for 2 h with CD2-a followed by 6 h of Dex regulated 5,219 gene probes, 971 of which were not affected by either Dex or CD2-a alone." (PMID 29867993, 2018). "After one day, CD4 + T cells cultured alone, stimulated by IEC, with or without anti-CD2 antibody, were infected, and GFP levels were measured on day 6 post-infection." (PMID 37202790, 2023). "Ex vivo, BAL CD2+ γδ T cells, without H1N1pdm09 stimulation, secreted IFNγ and TNF early post infection with the highest frequency of 0.6% IFNγ and 1.6% TNF at 3 DPI." (PMID 33603740, 2020). "Additionally, swIAV infection also led to an increase of cells represented by cluster 10 which consisted of CD3+ T cells that were negative for CD4, CD8β and TCR-γδ, but CD2+CD8α+perforindim." (PMID 40484956, 2025).
bacterial infection (2 papers, 2018). "Blockade or knockdown of Cd58 and Cd2 dramatically impaired the activation of antigen-specific Cd4+ T and mIgM+ B cells, followed by the inhibition of antibody production and host defense against bacterial infections." (PMID 29904386, 2018). "By knockdown and blockade of Cd58 or Cd2, the activation of antigen-specific Cd4+ Th cells was significantly impaired, mIgM+ B cell activation and Ab (IgM) production were inhibited, and defense against bacterial infections post-vaccination was diminished." (PMID 29904386, 2018). "As evidenced by the reduction in supernatant levels of IL-6, TNF-α, and IL-23 from CD2-a infected macrophages compared to bacterial infection without Dex, glucocorticoids appear to affect inflammatory cytokine secretion." (PMID 29867993, 2018).
immune diseases (1 paper, 2023). "It has been confirmed that genetic variation in CD2 is closely related to some immune diseases, and CD2 related signaling pathways have also been confirmed to be associated with virus clearance and autoimmune response enhancement." (PMID 37898694, 2023).
neurological diseases (1 paper, 2023). "We have demonstrated higher levels of CD8 and CD2 on CSF EVPs from patients with virus-associated neurologic diseases and infections in this cohort." (PMID 37622115, 2023). "In addition to HAM, elevated levels of CD8+ and CD2+ CSF EVPs were demonstrated in a limited number of virally associated chronic neurological disease carriers compared to patients with non-viral mediated neurologic disease." (PMID 37622115, 2023).
respiratory disease (1 paper, 2025). "Even though characteristics of patients in CD1 and CD2 suggested less severe disease (short length of stay and low mortality), by including these diagnosis codes the system would better capture RSV cases and respiratory disease among young children aged 0–4 years." (PMID 40843520, 2025).
CD2 also shares sentences with these, for which no sentence is quoted: head and neck cancer (3 papers); multiple myeloma (3); psoriasis vulgaris (3); cutaneous T cell lymphoma (2); hematologic malignancies (2); inflammation (2); kidney diseases (2); T-cell acute lymphoblastic leukemia (2); acute GVHD (1); adenocarcinoma (1); alexithymia (1); anaphylaxis (1); Anxiety (1); arthropathy (1); atopic dermatitis (1); bacterial vaginosis (1); cervical dysplasia (1); Colorectal (1); dermatomyositis (1); encephalitis (1); enteritis (1); Epstein-Barr virus infection (1); esophagus tumors (1); experimental autoimmune encephalomyelitis (1); fibrosarcoma (1); fibrosis (1); follicular lymphoma (1); gastric cancer (1); gastritis (1); germinoma (1).
A further 46 diseases each share a sentence with CD2 in 1 paper.